IL6 (interleukin 6)
Diseases named in the same sentence as IL6 in open-access papers (continued):
Sharing a sentence is not in itself a finding about the gene and the disease.
COVID-19 (continued). "Therefore, IL-6 and IL-6R are receiving more attention as potential therapeutic targets for the treatment of COVID-19." (PMID 33658032, 2021). "We hypothesized that COVID-19 patients carrying the high-producing IL-6 genotype were more likely to benefit from dexamethasone and IL-6 blockade therapy." (PMID 34634929, 2021). "Additionally, TNFα and MAPK promote the secretion of IL-6, contributing to the cytokine storm in COVID-19 patients." (PMID 34603282, 2021). "Our observations indicate that there is a correlation between increased CRP, ferritin, and IL-6 concentrations and the increased secretion of FLCs during COVID-19 in the group of patients hospitalized in the ICU (COVID ICU) and in other departments (COVID non-ICU)." (PMID 34372587, 2021). "It has been shown that SARS-CoV-2 spike (S) and nucleocapsid proteins alone can induce production of IL-6 in monocytes and macrophages, and such IL-6 upregulation may be a trigger that initiates the dysregulated immune response in some COVID-19 patients." (PMID 34835296, 2021). "Furthermore, we sought to evaluate the effects of the supplementation of 1α,25(OH)2D3 on IL-6 and 25(OH)D3 serum levels in a sub-group of COVID-19 patients with chronic renal failure and hypovitaminosis D." (PMID 34836187, 2021). "Increased serum levels of proinflammatory cytokines (TNF-α, IL-1, and IL-6) and chemokines (IL-8) have been found in patients with severe COVID-19, compared with individuals with mild disease, suggesting a possible role for a hyperinflammatory response in the pathogenesis of COVID-191,2." (PMID 34728719, 2021). "Another characteristic of severe COVID-19 patients is the cytokine storm: over-production of numerous cytokines and chemokines such as interleukin-6 (IL-6), tumor necrosis factor-α (TNF-α), monocyte chemotactic protein-1 (CCL2), and chemokine (C-X-C motif) ligand 10 (CXCL10)." (PMID 34764867, 2021). "Indeed, promising therapeutic effects of targeting IL-6 were recently reported in severe COVID-19 patients." (PMID 33811756, 2021). "Biobanked samples from ongoing tocilizumab clinical trials in COVID-19 and other diseases may provide an opportunity to validate IL-6 module performance in this way." (PMID 33319166, 2021). "It should be noted that the role of IL-10 in blocking the activity of IL-6 may be impaired in COVID-19 patients; however, further studies are needed to confirm this theory." (PMID 34251989, 2021). "Thus, IL-6 stands as a pleiotropic biomarker for CNS and respiratory system dysregulation among which AD and COVID-19 worth mentioning." (PMID 33078369, 2021). "Hence, serum levels of IL-6 are higher (100–10000 pg/mL) in COVID-19 patients compared to healthy controls." (PMID 35126355, 2021). "There is controversy whether IL-6 (receptor) antagonists are beneficial in treating COVID-19 patients." (PMID 34728658, 2021). "Moreover, specific cytokines such as IL-6, interleukin-8 (IL-8), and interleukin-10 (IL-10) are higher in patients with COVID-19-related ARDS." (PMID 34938289, 2021). "Among these factors include the unknown role of immunomodulator drugs such as corticosteroids and interleukin-6 antagonists in COVID-19 treatment." (PMID 34809657, 2021). "It has been suggested that ‘cytokine storm’ or the enhanced production of inflammatory cytokines, especially IL-6, may lead to the activation of the coagulation cascade in COVID-19 patients." (PMID 34103044, 2021). "Furthermore the results from the WHO Rapid Evidence Appraisal for COVID-19 Therapies (REACT) Working Group, meta-analysis on only RCTs, confirmed our conclusion that IL-6 (receptor) antagonists are associated with lower mortality for patients with COVID-1922." (PMID 34728658, 2021).
COVID-19 (continued). "Take in account this idea, it would be expected that severe COVID-19 group showed imbalance between higher IL-6 levels and/or lower IL-10 levels, showing an impairment control of inflammation, which was associated with increased upper airway symptoms, as observed in our previous studies." (PMID 33717074, 2021). "Therefore IL-6 is considered to be the key player in COVID-19 cytokine storm an entity characterized by fever, hypoxia (due to acute lung injury with lung infiltrates on imaging and raised inflammatory markers)." (PMID 33673818, 2021). "The administration of TCZ in an early stage of cytokine storm (IL-6 level < 100 pg/ml) may effectively improve the clinical prognosis of patients with COVID-19 by blocking the IL-6 signal pathway." (PMID 33937333, 2021). "Assuming that subjects with severe infection can benefit from suppression of cytokine release syndrome, a large number of clinical trials aimed to investigate the efficacy of anti-inflammatory therapy including anti-IL-1, anti-IL-6 agents and steroids in patients with COVID-19 were started." (PMID 34586459, 2021). "Clinical trials evaluating IL-1 and IL-6 inhibitors in COVID-19 are ongoing." (PMID 33658050, 2021). "Activation of the STING (stimulator of interferon genes) pathway which contribute to over-immune response observed in Kawasaki disease and COVID-19, is inhibited by aspirin, intravenous immunoglobulins, vit D and anti-IL-6, potentially being beneficial in these conditions." (PMID 33763085, 2021). "More importantly, critical but deceased COVID-19 patients showed high levels of several proinflammation cytokines, such as IL-2R, IL-8, and IL-6, and anti-inflammatory cytokine IL-10 in vivo, which resulted in lymphopenia, multiple organ failure, and the rapidly decreased nAb response." (PMID 34712742, 2021). "The role of IL-6, IL-1β, and TNFα in those suffering with COVID-19 is somewhat contradictory, with conflicting reports of these markers being linked to both mild disease and more severe cases typified by the occurrence of an inflammatory syndrome and a dysregulated proinflammatory response." (PMID 35222355, 2021). "Furthermore, we used the IL-2R/IL-6 and TNF-α/IL-6 ratios on behalf of the Th1/Th2 ratios to determine which type of T-helper cells was dominant in the progression of COVID-19." (PMID 33776910, 2021). "Thus, nicotine inhibition is being considered a potential therapy against the elevated IL-6 levels in COVID-19 patients." (PMID 34452063, 2021). "Similarly, miR-6741 was found to target many APOL1-related genes in COVID-19, increasing pro-inflammatory cytokines IL-6, IL-10, and IL-18, and CC chemokine ligand 5 (CXCL-5)." (PMID 35062245, 2021). "Importantly, the levels of TNF- α, IL-2R, IL-6, IL-8, and IL-10 were significantly correlated with survival time of cancer patients with COVID-19." (PMID 33735106, 2021). "Some hypotheses concerning low Treg levels in COVID-19 patients suggested that low IL-2 parallel with high IL-6 in severe cases leads to enhanced apoptosis of Treg cells." (PMID 34071149, 2021). "Moreover, elevated levels of the inflammatory indicator IL-6 in the blood have been reported to be predictive of a fatal outcome in COVID-19 patients." (PMID 33390771, 2021). "Thus, increased serum IL-6 level is a common indicator of respiratory complications occurred in COVID-19." (PMID 33078369, 2021). "Only two RCTs reported the effect of oral CHM as an adjuvant on IL-6 during COVID-19." (PMID 35127733, 2021). "Patients with COVID-19, compared with those with influenza, have higher concentrations of a few cytokines (ie, interleukin 6 [IL-6] and interleukin 1 receptor antagonist [IL-1ra]), lower concentrations of most cytokines, and profound type I and type II interferon immunosuppression." (PMID 34032853, 2021).
COVID-19 (continued). "Interestingly, quantitative proteomic analysis that the authors carried out in the third part of the study showed up-regulation of IL-8 and IL-6 in peripheral blood mononuclear cells (PBMCs) isolated from severe COVID-19 patients in comparison to mild ones." (PMID 33430309, 2021). "As an upstream regulator of the exosomal proteins in COVID-19 patients, we speculate that IL-6 may also affect protein secretion from cells through EVs." (PMID 33693030, 2021). "These factors may explain the discordance recorded between IL-6 gene expression and protein secretion in COVID-19." (PMID 33319166, 2021). "Consistent with this hypothesis, levels of CRP, ferritin, IL-6, IL-8, and tumour necrosis factor alpha are significantly increased in deceased patients with COVID-19 compared to those who survived and are independent predictors of survival." (PMID 33824762, 2021). "Correlation between redox biomarkers and immunological or multiorgan impairment biomarkers, as well as pulmonary CT pattern, confirms the suggested involvement of neutrophils networks, IL-6 production, along with different organ/tissue involvement in systemic oxidative stress in COVID-19." (PMID 34356359, 2021). "A large peer-reviewed study with 1,018 participants reported over ten-fold increases in IL-6 levels amongst COVID-19 cases, and found that serum IL-6 >20pg/mL was strongly associated with in-hospital mortality (OR 9.78, p<0.001) on multivariable regression analysis." (PMID 33493185, 2021). "In addition, DFO decreases IL-6 and endothelial inflammation 123, the most important mechanism related to multiorgan damage and failure among COVID-19 patients." (PMID 33390800, 2021). "Moreover, elevated IL-6 and CRP level and lymphopenia were found to be positively associated with disease severity and prognosis of patients with COVID-19." (PMID 33746189, 2021). "A retrospective review of medical reports and records from hospitalized COVID-19 patients admitted to the Shenzhen Hospital from 11 January to February 23, 2020 showed that COVID-19 patients receiving ARBs or ACEIs had a lesser disease severity and low level of IL-6 in peripheral blood." (PMID 34806090, 2021). "This lends support to our findings that Streptococcus sanguinis SK1 = NCTC 7863 may influence the immune response to COVID-19 by upregulating inflammatory IL-6 signaling and downregulating IL-4 signaling." (PMID 34200572, 2021). "Ninety-nine of 115 (86.1%) COVID-19 patients had elevated levels of IL-6." (PMID 34123873, 2021). "In addition, a decrease in the expression of IL-6 was observed, which is related to severe symptoms of COVID-19." (PMID 34458372, 2021). "All patients received the best supportive care and specific interventions that included the main drugs being tested for repurposing to treat COVID-19, such as hydroxychloroquine, anticoagulation and antiviral drugs, steroids, and interleukin-6 pathway inhibitors." (PMID 34208017, 2021). "The latest studies published until July 1, 2021, were retrieved from databases including PubMed, Embase, and Cochrane Library to analyze the ability of lymphocyte and platelet counts as well as interleukin-6 levels to predict mortality in patients with COVID-19." (PMID 34938342, 2021). "Relevance of IL-6 to specifically COVID-19 has been more intensively investigated." (PMID 34163532, 2021). "Reports have revealed increased levels of IL-6 in critically ill COVID-19 patients." (PMID 34649460, 2021). "Furthermore, elevated levels of IL-6, a hallmark of severe MERS-CoV infection, is common in COVID-19 patients with respiratory failure and ARDS." (PMID 34205044, 2021). "Indeed the level of IL-6 in COVID-19 patients was reported to be lower than in other diseases attributed to cytokine overproduction." (PMID 34149697, 2021). "Immunologically, depleted Zn2+ level might shift the Th1/Th2 balance to Th2 predominance resulting in increased IL-6 generation of COVID-19 subjects." (PMID 33078369, 2021).
COVID-19 (continued). "The data above suggest that the immunogenetic profiling of IL-6 and IFN gamma genes may be of use in weaving out the individuals at higher risk of cytokine storm while having COVID-19." (PMID 34149697, 2021). "Intriguingly, although both NLR and IL-6 are efficient biomarkers for the prediction of the disease severity and survival of COVID-19 in this study, none of them is significantly associated with the duration of illness." (PMID 33584733, 2021). "Therefore, IL-6 has been determined to be an important target for treatment of COVID-19, and the IL-6 inhibitors are potential drugs against the virus infection." (PMID 33717061, 2021). "Interestingly, serum levels of IL-6, a cytokine identified as playing an essential role in the pathogenesis of COVID-19, were decreased after the second dose of vaccine." (PMID 34681885, 2021). "Thus, we selected IL-6, IL-8, IL-10 and IP-10 as the cytokines with the highest performance in the discrimination of mild COVID-19, severe COVID-19 patients and healthy volunteers." (PMID 34675240, 2021). "Studies have shown that increased inflammatory markers such as IL-2, IL-6, macrophage inflammatory protein 1-α or coagulation dysfunction in patients with severe COVID-19 may increase the likelihood of stroke compared with moderate patients." (PMID 34425827, 2021). "IL-6 and TNFα were significantly elevated in COVID-19 patients, which might result in low LDL-C level." (PMID 34504873, 2021). "The serum level itself, however, cannot be used solely for validation the role of IL-6 in the pathomechanism of COVID-19 as the deteriorating effect of this inflammatory cytokine depends also on the susceptibility of the targeted organ which is higher if concomitant disease exists." (PMID 34149697, 2021). "In addition, our immunofluorescent staining also showed co-localization of IL-2 with IL-6 was primarily in maternal blood in COVID-19 placentas." (PMID 35071136, 2021). "As such, RCTs are being conducted to examine the efficacy of IL-6 blockade in COVID-19 patients." (PMID 34176095, 2021). "Likewise, serum IL-1β, IL-6, and IL-8 levels were positively correlated with critical COVID-19 in-hospital death (r = 0.4929; r = 0.4539; r = 0.6002, respectively)." (PMID 34276659, 2021). "Discharged patients who had COVID-19 might still have a high level of IL-6, and more attention should be paid to the inflammatory levels of patients, even after the discharge." (PMID 33746945, 2021). "The OR value of IL-6 adjusted for preceding dexamethasone administration showed a high value, indicating that IL-6 levels might reflect an ongoing respiratory deterioration in COVID-19 patients even under the dexamethasone therapy." (PMID 34441262, 2021). "The observations of laboratory abnormalities in severe COVID-19 coincide with each other in the following aspects: severely ill patients were reported to present higher levels of IL-6, D-dimers, LDH, platelets, hsCRP, white blood cells with predominant neutrophils, and fewer lymphocytes." (PMID 34209289, 2021). "Moreover, the current study conducted during a different wave of the pandemic confirmed the previous report that higher IL-6 levels and more frequent pulmonary infiltration were detected in COVID-19 patients with headache." (PMID 34384355, 2021). "Consistent with previous descriptions of disease, our patients with severe COVID-19 were more frequently males, had lower lymphocyte count, and higher serum values of C-reactive protein, lactate dehydrogenase, procalcitonin, D-dimer, and interleukin 6 than patients with mild-to-moderate COVID-19." (PMID 33481096, 2021). "Indeed, higher than normal IL-6 levels are detected in COVID-19 patients requiring hospitalization or with acute respiratory failure." (PMID 33981312, 2021).
COVID-19 (continued). "There were statistically significant increments of serum IL-6, IL-8 and IL-10 levels in patients with COVID-19, consistent with the hyperinflammatory syndrome that is so characteristic of severe and progressive disease, which rapidly dropped during convalescence." (PMID 33060840, 2021). "Notwithstanding this, some authors have hypothesized that the role of IL-6 merely serves as a reliable biomarker for the early detection and progression of COVID-19." (PMID 33975613, 2021). "IL-6 is also known to be a key element in the cytokine storm observed in severe COVID-19 patients." (PMID 34421600, 2021). "The consequences of these protein interactions need to be experimentally elucidated, however our results suggest that altered levels of TNF, IL-6 and CXCL9 in COPD patients may be involved in the initial steps that predispose COPD patients to severe COVID-19." (PMID 34335580, 2021). "Therefore, potential targeting of IL6 induced by IL1B is an exciting therapeutic approach in COVID-19." (PMID 33757410, 2021). "Alterations in IL-6 and IL-6R genes could be involved in the onset and progression of several diseases, including infectious diseases, such as COVID-19, and neurodegenerative diseases, such as AD." (PMID 33673697, 2021). "Taken together, endothelial dysfunction (elevated vWF level), with the release of fibrinolysis inhibitor PAI-1, and hyperimmune response (increased ESR, CRP, ferritin, and IL-6) with younger (higher H-IPF) activated platelets seem to be significant contributors to thrombogenesis in COVID-19." (PMID 34940584, 2021). "Altogether, these results suggest that both pulmonary and extrapulmonary tissues may play important role in the dysregulated levels of interleukins (e.g. IL-6 and IL-1), interferon-gamma, and tumor necrosis factor superfamily cytokines in COVID-19 patients." (PMID 34262555, 2021). "Furthermore, the patients with severe COVID-19 had significantly higher concentrations of sRAGE and IL-6 (biomarkers of inflammation)." (PMID 34214123, 2021). "Recent studies found IL-6 elevation in COVID-19 patients and IL-6 antagonists might bring benefits to the patients with severe COVID-19 symptoms." (PMID 34595243, 2021). "According to recent studies, IL-6 may be responsible for severe lung inflammation and pulmonary function disability in patients with severe COVID-19." (PMID 34439868, 2021). "Their blockade could avoid deleterious effects due to the hyperexpression cytokine and protecting brain cells, suggesting that the use of IL6 antibodies in COVID-19 cases blocks the action against several tissues." (PMID 34577633, 2021). "A double-blinded randomized controlled trial demonstrated that Xuebijing injection may suppress the cytokine storm and prevent the progression to ARDS in severe COVID-19 patients by regulating the secretion of pro-inflammatory cytokine IL-6, IL-8, and TNF-α." (PMID 34421581, 2021). "We then analyzed three major inflammatory cytokines reportedly associated and possibly causally involved in COVID-19 pathology irrespective of outcome, namely IL-6, IL-8 and TNF." (PMID 34943881, 2021). "Experiments performed with ex vivo freshly isolated monocytes showed that unstimulated monocytes from patients with COVID-19 were able to spontaneously secrete high levels of IL-6, IL-8 and IL-1β which persisted, even though at lower levels, in recovered individuals for several weeks after recovery." (PMID 33060840, 2021). "For this reason, therapies targeting the host immune system may be effective for COVID-19; in particular, IL-6 blockade, e.g., by inhibiting NF-kB signaling, seems to be the most promising strategy." (PMID 33808471, 2021). "However, before regarding IL-6-mediated CRS as the pathological driver of severe COVID-19, caution should be warranted." (PMID 33628091, 2021). "The serum concentration of IL-6, IL-8 and IL-10 might be considered as a reflective sign of the COVID-19 severity." (PMID 33914789, 2021).